CD47 (CD47 molecule)
Diseases named in the same sentence as CD47 in open-access papers (continued):
Sharing a sentence is not in itself a finding about the gene and the disease.
tumor (continued). "These pro-tumorigenic effects may be blocked by blocking the TSP-1/CD47 axis, but possibly at the expense of anti-tumor results." (PMID 36429020, 2022). "However, experimental administration of monoclonal antibodies or soluble SIRPα (Fc-fusion) that bind CD47 and block the CD47-SIRPα signaling pathway promotes tumor cell phagocytosis, inhibits tumor growth in mice, and increases survival." (PMID 36369063, 2022). "CD47 blockade can be effective by lowering the threshold for macrophage phagocytosis, while tumor-binding antibodies may be able to direct macrophages against tumors for greater specificity." (PMID 36429020, 2022). "Ligation of SIRPα by its ligand CD47 limits effector functions and thereby tumor cell elimination." (PMID 35884427, 2022). "M1 Exo-Abs accumulated in tumor cells overexpressing CD47 due to aCD47." (PMID 36460660, 2022). "In the fourth pathway, the inhibition of CD47 or SIRPα can induce tumor cell apoptosis, which could be attributed to the direct ligation of CD47 rather than the caspase-dependent pathway." (PMID 35860564, 2022). "However, CD47 is highly expressed on the surface of tumor cells, which serves as a mechanism for evading immunodetection." (PMID 35892835, 2022). "LSD1 inhibitor combined with anti-CD47/PD-L1 monoclonal antibodies could more effectively inhibit tumor growth in a subcutaneous xenograft model because of increasing the expressions of CD47 and PD-L1." (PMID 36397138, 2022). "List of anti-tumor clinical trials targeting CD47-SIRPα axis." (PMID 35557862, 2022). "Although the significance of CD47 expression in tumors has been identified in many tumor types, the role of SIRPα in ICC patients remains unclear." (PMID 35317832, 2022). "On the one hand, due to the targeting of anti-CD47 antibodies, the exosome nanobioconjugates could effectively accumulate in tumor tissues and then release antibodies." (PMID 35664074, 2022). "As an approach to selectively target CD47 on cancer cells, we have developed a fully human IgG1 bispecific antibody (bsAb) platform, which takes advantage of the fully competent Fc effector functions of human IgG1 and avoids on-target/off-tumor toxicity of CD47." (PMID 35538512, 2022). "In addition, CD47 was also overexpressed on hematologic and solid malignancies, and treatment with agents that block CD47-SIRPα interaction stimulated macrophage phagocytosis in vitro and anti-tumor responses in vivo." (PMID 35418166, 2022). "As with targeting CD4, designing multipronged CAR-T cells under a subsequent “HELP” gate framework, where a CD47 CAR assists T cells to bind with tumor cells first, followed by the ligation of the second CAR with another target antigen, may be possible." (PMID 36059451, 2022). "DSF/Cu-mediated enhancement of tumor immunogenicity improved CD47 blockade efficacy in HCC." (PMID 36230638, 2022). "Moreover, treatment with antibodies to SIRPα or to CD47 promoted antigen cross-priming of CD8+ T cells by cDC2s as well as enhanced the antitumor effect mediated by CTLs in a mouse syngeneic tumor model in vivo." (PMID 35454882, 2022). "Previous studies have shown that blocking the CD47-SIRPα signal could not only restart phagocytosis but also enhance tumor antigen presentation and activate specific antitumor immune response, reacting in both innate and adaptive immunity." (PMID 35422796, 2022). "As a new immune checkpoint molecule, CD47 on tumor cells is combined with signal-regulatory proteinα(SIRPα)to send “don’t eat me” signal to immune system, playing a key role in tumor cells recognition and immune escape, and gradually becoming an effective target of tumor immunotherapy." (PMID 36211357, 2022). "The introduction of a tumor-specific targeting arm into CD47-based BsAbs may potentially restrict CD47-SIRPα blockade to the tumor site." (PMID 35132063, 2022). "STI-6643 killing activity was evaluated on CCRF-CEM tumor cells expressing high CD47 levels." (PMID 35664753, 2022).
tumor (continued). "Moreover, the effector phenotypes of virus-specific as well as the tumor-infiltrating CD8+ T cells significantly decreased in Cd47−/− mice." (PMID 36105746, 2022). "The cluster of differentiation 47 (CD47) is universally expressed on normal cells, and tumor cells regulate phagocytosis and cytotoxic activity of myeloid cells through interaction with the signal‐regulatory protein α (SIRPα) receptor on myeloid lineage derived cells." (PMID 36054073, 2022). "Consequently, IBI322 uptake was increased in PD‐L1‐CD47‐positive tumours and decreased in blood depot organs compared to the parental CD47 mAb." (PMID 35908284, 2022). "This could be further exacerbated by the use of non-tumor-specific anti-CD47 antibodies triggering the potent combination of PMN-mediated cytotoxicity described herein." (PMID 35795660, 2022). "In contrast, the blockade of CD47 with a monoclonal antibody enables phagocytosis of tumor cells." (PMID 35978433, 2022). "It is important to note that some anti-CD47 antibodies can by themselves opsonize tumor cells, depending on their ability to still bind Fc-receptors, and hence act as a two-edged sword, i.e., by opsonizing tumor cells for phagocytosis and simultaneously inhibiting CD47-SIRPα interactions." (PMID 35884427, 2022). "Furthermore, the anti-tumor effcacy of cotreatment with bevacizumab and anti-CD47 antibody has been demonstrated in BGC-823 gastric xenograft mouse model." (PMID 35694254, 2022). "It is, therefore, likely that immunotherapy targeting the CD47/SIRPα axis may enhance anti-tumor response by activating both macrophage-mediated innate and T-cell adaptive immunity." (PMID 35406573, 2022). "CD47, a “don’t eat me” signal, is a phagocytosis inhibitor expressed on almost all cancer cells, and the ability of P. gingivalis to upregulate the expression level of cd47 in cancer cells may be another mechanism to accelerate tumor development." (PMID 35967399, 2022). "When CD47 is expressed on tumor cells, it enables them to evade the immune system." (PMID 36611344, 2022). "In vivo study further showed that CD47 blockade could effectively reeducate microglia in the GBM tumor microenvironment to unleash the therapeutic potential of tumor cell phagocytosis." (PMID 35428347, 2022). "The preclinical evidence that inhibition of the CD47-SIRPα checkpoint may promote the efficacy of tumor-directed therapeutic antibodies has prompted the clinical development of a variety of compounds targeting CD47-SIRPα." (PMID 35884427, 2022). "It was confirmed that CD47 upregulation in refractory lung tumor models was mediated by the TNF-α/NF-κB1 signaling pathway, and blocking CD47 could enhance anti-tumor effects." (PMID 36523419, 2022). "Indeed, CD47 protein level was enhanced by radiation (IR 5 Gy) in WT tumor cells and remarkedly elevated in RR GBM cells." (PMID 35314680, 2022). "Therefore, a high expression of CD47 in tumor-infiltrating immune cells would protect these cells against macrophage-mediated phagocytosis and ensure a better response to ICI immunotherapy." (PMID 36171566, 2022). "Here, we find that the anti-tumor activity of macrophages reprogrammed by PARP inhibition can be harnessed through added blockade of the don’t-eat-me signal CD47, a combination that could potentially be studied in clinical trials." (PMID 36223740, 2022). "However, live tumor cells are actively phagocytosed by microglia after administration of functional blocking antibody for CD47." (PMID 35142399, 2022). "All the data presented so far underscore the role that CXCR4 and CD47 play in tumor promotion." (PMID 36293358, 2022). "Blocking the CD47/SIRPα cross talk has been shown to enhance anti-tumor activities." (PMID 35978372, 2022).
tumor (continued). "Under hypoxia, activation of HIFs and their downstream signaling pathways (including CXCR4, M-CSFR, and CD47) regulate the tumor-specific immune response, with production of several immunosuppressive cytokines and growth factors to allow for immune escape and promoted tumor progression." (PMID 35659268, 2022). "FAS expression was positively associated with CD18, CD47 and IRF47, which suggested that FAS may also help the migrated tumour cells survive from the immune surveillance." (PMID 35685372, 2022). "Our results showed that DSF/Cu alone or anti- CD47 alone could inhibit tumor growth, while the combination of two drugs had a more pronounced effect." (PMID 36230638, 2022). "In fact, the release of DAMPs, including the eat-me signal calreticulin, may be necessary in addition to CD47 surface depletion to induce phagocytosis by macrophages, and may allow the discrimination of tumor cells from healthy cells." (PMID 35565443, 2022). "In other words, MYC signaling leads to increased expression of CD47 and PD-L1 in tumor cells." (PMID 37305016, 2022). "Systemic tumor growth was measured by bioluminescence revealing a significant anti-tumor activity induced by anti-CD47 mAbs when compared to isotype control correlating with a prolonged survival of STI-6643 (73%) and Hu5F9 (60%) treated mice as compared to isotype (0%) treated mice." (PMID 35664753, 2022). "Tumor cells express high level of CD47 to escape immune surveillance initiated by macrophages, which leads to the development of CD47-SIRPα blockade as a promising approach for cancer therapy." (PMID 35511221, 2022). "Targeting the CD47–SIRPα axis could be an anti-tumor strategy to restore immunity functions and improve the prognosis of GBM patients." (PMID 35954362, 2022). "After CaCE inoculation, we tested the expression level of CD47 in the tumor tissue." (PMID 36054073, 2022). "Functionalization with CD47-blocking antibody was dedicated to inhibit `don ́t-eat-me ́ signaling by tumor cells, which may express this receptor at high level." (PMID 35693776, 2022). "Moreover, the correlation coefficient values between GPR35 and tumor-associated macrophage markers (VEGF and CD47) were all positive (p < 0.05)." (PMID 36333291, 2022). "Indeed, the advent of novel monoclonal/bsAb formats and combination strategies point towards the clear potential for increased tumour selectivity and efficacy and reduced toxicity of CD47‐SIRPα‐based immunotherapy." (PMID 35908284, 2022). "These preclinical studies have demonstrated that blocking the CD47-SIRPα interaction, by either mAbs or BsAbs, may promote tumor cell killing by myeloid cells such as neutrophils and macrophages." (PMID 35884427, 2022). "Notably, macrophage removal restored tumor development after CD47 blockage, illustrating that macrophages play an indispensable role in preventing cancer cell growth following CD47 dampening." (PMID 35978372, 2022). "Thus, the binding of DSP107 to tumor-overexpressed CD47 enables its 4-1BB agonistic activity and helps drive T cell immune responses." (PMID 35287686, 2022). "Therefore, we decided to examine the potency of combination therapy of single high dose RT plus anti-CD47 immune checkpoint inhibitor compared to single therapies for tumor control." (PMID 36018888, 2022). "By investigating the expression of CD47 on tumor surface, it was found that PQ/PB-Gel could reduce the expression of CD47 on tumor surface almost to achieve the same effect as aCD47 blocking." (PMID 35832081, 2022). "In addition, the treatment of SIRPα-exosomes can promote T cell infiltration in syngeneic tumor mouse model and increase the possibility of CD47 targeting therapy to release innate and adaptive antitumor responses." (PMID 34973131, 2022). "The effective tumor control by CD47 immunotherapy is being increasingly demonstrated." (PMID 35314680, 2022).
tumor (continued). "The overexpression of CD47 on tumor cells suggested that blockade of the “don’t eat me” checkpoint could synergize with therapeutic mAbs to enhance the elimination of tumors by myeloid cells." (PMID 35795660, 2022). "The presence of CD47 enhanced exhaustion phenotype of CD8+ T cells in the tumor microenvironment." (PMID 36105746, 2022). "Interestingly, the adaptive immune system plays a major role in the anti-tumor activity of anti-CD47 inhibitors." (PMID 35883692, 2022). "Therefore, based on the specific immune signature of the TNBC tumor environment, where the immune checkpoint molecules CD47 and PD-L1 are over-expressed, we present here three novel dual-targeting fusion proteins for the treatment of TNBC." (PMID 36009390, 2022). "Soluble SIRPα binding to CD47 on tumor cells could block inhibitory signals and enhance phagocytic activity." (PMID 35418166, 2022). "Given that increased PD1 and SIRPα were observed in ICC patients in the present study, we speculate that anti-CD47 in combination with anti-PD1 may achieve better anti-tumor effects in ICC patients." (PMID 35317832, 2022). "Both in vitro and in vivo studies demonstrated that NAcp@CD47 could increase the polarization of M1-phenotype TAMs, help reduce tumor immunosuppression, and inhibit tumor growth by phagocytosis of macrophages and microglia." (PMID 35910792, 2022). "Thus, anti-CD47 is suggested efficacious by promoting immune response ablating tumor cells via macrophage and/or DCs, even through microglia." (PMID 35135556, 2022). "In addition, early studies revealed a role for anti-CD47 mAbs in the priming of an adaptive immune response leading to enhanced anti-cancer activity by expanding tumor-specific cytotoxic T cells." (PMID 35664753, 2022). "Immunosuppressive effects of RT in the TME include an increased infiltration of regulatory T cells (Tregs), M2 tumor-associated macrophages (TAMs), and MDSCs, along with the expression of immune checkpoints molecules such as PD1/PDL1, CTLA4, and CD47 on tumor cells." (PMID 36018888, 2022). "Cancer cells can express high levels of CD47 to circumvent tumor elimination." (PMID 35884427, 2022). "The distinct co-expression pattern of PD-L1 and CD47 in cancers compared to normal tissues provides a rationale for designing BsAbs that can selectively recognize PD-L1+CD47+ tumor cells and block their CD47 signaling to trigger the engulfment of double-positive cancer cells." (PMID 35978372, 2022). "The targeting of CD47 is being tested in clinical trials for the treatment of various tumor types." (PMID 35164813, 2022). "However, the expression of IL-7 receptor (CD127) in both spleen and tumor infiltrating CD8+ T cells was significantly higher in Cd47−/− than in WT mice, suggesting early differentiation of effector to central memory T cells in the absence of CD47." (PMID 36105746, 2022). "In triple-negative breast cancer, CD47 expression showed 2.3-fold higher in cancer stem cells (CSCs) than the normal counterparts by Gene Set Enrichment Analysis, and this upregulation was closely related to tumor growth." (PMID 35860564, 2022). "Therefore, we developed an adenovirus-based tumor vaccine loaded with a CD47-targeting nanobody fused with the IgG2a Fc protein." (PMID 35837100, 2022). "However, tumor cells overexpress CD47 to evade the immune system through inhibition of myeloid cell-mediated elimination." (PMID 35418166, 2022). "CD47 mAbs suppressed the CD47–SIRPα axis, thus activating TAMs to phagocytose tumor cells." (PMID 36587223, 2022). "It is worth noting that SIRPα-exosomes can shorten the time required for exosomes to reach the tumor target of CD47 overexpression, and only low-dose SIRPα-exosomes can effectively inhibit the growth of tumor in vivo by blocking CD47-SIRPα, so as to improve the therapeutic effect." (PMID 34973131, 2022).
tumor (continued). "A combination of blockade of the CD47-SIRPα axis and secondary targets in the tumor microenvironment (TME) may improve the clinical efficacy of current immunotherapeutic approaches." (PMID 36429020, 2022). "In addition, we analyzed the immune checkpoint PD-1 and CD47 and demonstrated their high expression in tumor tissues compared with normal tissues, which shows the feasibility of anti-PD-1 and anti-CD47 antibodies in the immunotherapy of HCC." (PMID 35559014, 2022). "Blockade of the interaction between CD47 and SIRPα could restore phagocytic activity and eliminate tumor cells in vitro and in vivo." (PMID 35418166, 2022). "Thus, disruption of the SIRPα-CD47 axis would protect effectively against solid tumors by inducing tumor phagocytosis." (PMID 35585567, 2022). "Furthermore, anti-CD47 therapy has been shown to promote the polarization of TAMs from an M2- to an M1-like phenotype and induce anti-tumor effects." (PMID 36466873, 2022). "Studies have reported that CD47 expression implies higher tumorigenicity and tumor progression." (PMID 35559014, 2022). "In addition to the inhibition of macrophage-mediated phagocytosis, CD47 expressed on tumor cells was shown to inhibit the detection of tumor cell–derived mitochondrial DNA by SIRPα on DCs, resulting in attenuation of type I IFN production by DCs." (PMID 35454882, 2022). "A recent study provided substantial evidence suggesting that blockage SIRPα/CD47 axis could enhance adaptive immunity and prime an anti-tumor cytotoxic T-cell response." (PMID 35874659, 2022). "Moreover, for tumors, “self-markers” such as CD47 presented on PVs allow them to evade immune clearance, thereby prolonging circulation time and preferentially accumulating at tumor sites through enhanced permeability and retention effect." (PMID 35399954, 2022). "The activation of CD47 may induce the growth of tumor cells and accelerate the proliferation and transformation." (PMID 35433462, 2022). "The bsAb NI‐1701 was designed for the tumour‐selective targeting of CD47 to CD19." (PMID 35908284, 2022). "Chemotherapy administered before anti-CD47 therapy may not only be synergistic but also might preserve memory immune response preventing tumor relapse." (PMID 36429020, 2022). "The fibrinogen solution containing anti-CD47 antibody-loaded calcium carbonate NPs, and another thrombin solution could quickly mix by the spray set in the post-operative tumor resection cavity, leading to the formation of fibrin gel." (PMID 35664074, 2022). "Therefore, blockade of the CD47–SIRPα interaction represents a promising strategy for tumor immunotherapy." (PMID 36970051, 2022). "Importantly, CD47 KO tumor nodules treated with anti-Tyrp1 show many F4/80-positive cells that are round in morphology and contain a single large nucleus plus some melanization." (PMID 35454837, 2022). "However, the efficacy of anti-CD47 therapy is largely dependent on the expression of CD47 within the tumor microenvironment (TME)." (PMID 36171566, 2022). "For example, CD47 promotes immune escape and is overexpressed on many tumor cell surfaces." (PMID 36051588, 2022). "However, emerging studies have reported that HIF-1 directly activates CD47 gene transcription in hypoxic tumour cells." (PMID 35694254, 2022). "The aggressive phenotypes attributes to the fact that CD47 promotes tumor cell growth and motility." (PMID 36291980, 2022). "CD47+ TIICs were significantly higher in the tumor periphery compared to the tumor center." (PMID 36171566, 2022). "SIRPα binds to CD47, a receptor frequently overexpressed on cancer cells, and this interaction provides a “do-not-eat-me” signal to prevent phagocytosis, which plays a pivotal role in tumor progression." (PMID 35585990, 2022). "But it still triggered potent macrophage-mediated phagocytosis against human hematological cells, suggesting that CD47-SIRPα blockade alone may be sufficient to induce tumor regression." (PMID 36081498, 2022).